TTK (TTK protein kinase)
Diseases named in the same sentence as TTK in open-access papers (continued):
Sharing a sentence is not in itself a finding about the gene and the disease.
esophageal cancer (7 papers, 2012 to 2025). A primary or metastatic malignant neoplasm involving the esophagus. "The results showed that TTK expression was higher in esophageal cancer tissues than in normal tissues, and TTK expression levels in tumor stages 1–3 were significantly increased." (PMID 38658569, 2024). "TTK has been identified as one of the promising candidates for vaccination in esophageal cancer patients with advanced stage disease." (PMID 34031527, 2021). "To provide ideas for the role of the cancer–testis antigens MAGE-A, NY-ESO-1, LAGE-1, and TTK in esophageal cancer, we summarized their expression, prognostic value, and development in immunotherapy." (PMID 30656409, 2019). "In this review, we summarize expression and prognostic value of MAGE-A, NY-ESO-1, LAGE-1, and TTK in esophageal cancer and point out recent advances in immunotherapy about them." (PMID 30656409, 2019). "Notably, treatment of patients with advanced esophageal cancer with a multi-CTA vaccine against TTK, LY6K and IMP3 (NCT00682227) induced specific T cell immunity and resulted in clinical responses in 50% of patients." (PMID 38596293, 2024). "TTK has also been reported as a downstream molecule of microRNA-335-5p in esophageal cancer." (PMID 38658569, 2024). "Here, we investigated proteins that interact with TTK in esophageal cancer by mass spectrometry." (PMID 38658569, 2024). "The clinicopathological significance of cancer–testis antigens, especially MAGE-A, NY-ESO-1, LAGE-1, and TTK has gradually become clear through the efforts of many researchers, but the role of cancer–testis antigens in the development of esophageal cancer is still unclear." (PMID 30656409, 2019). "Hence, this review aims to focus on CT antigens MAGE-A, NY-ESO-1, LAGE-1, and TTK, and discuss their expression, prognostic value and targeted immunotherapeutic strategies in esophageal cancer." (PMID 30656409, 2019). "Similarly, two other studies have shown that TTK mRNA level is increased in esophageal cancer." (PMID 30656409, 2019). "The potential mechanism of action of TTK in esophageal cancer, however, has not been thoroughly studied." (PMID 38658569, 2024). "Although TTK inhibitor is a promising treatment method, there are no published studies on the application of this therapy to esophageal cancer presently." (PMID 30656409, 2019).
thyroid cancer (7 papers, 2018 to 2023). "The overexpression of TTK has been associated with various human malignancies, including breast, colorectal and thyroid carcinomas." (PMID 36405310, 2022). "Expression levels of TRIP13, TPX2, DLGAP5, KIF2C and TTK were associated with shorter disease free survival (DFS) among differentiated thyroid cancer." (PMID 30386706, 2018). "TTK overexpression is detected in many cancer types including, breast, hepatocellular and thyroid carcinomas." (PMID 36405310, 2022). "Compared with normal thyroid tissue, 7 CRGs were more highly expressed in thyroid cancer, namely BUB1 (P<0.001), RPL3 (P<0.001), TTK (P<0.001), GINS2 (P<0.001), SLC26A6 (P<0.001), CDKN2A (P<0.001) and ZNHIT2 (P<0.001)." (PMID 37745716, 2023).
breast tumors (4 papers, 2014 to 2022). "Analyzing TTK expression across tumor grades indicated high TTK expression significantly correlated with grade III breast tumors compared to grades I or II tumors." (PMID 30206215, 2018). "NHW women with Her2 + breast tumors significantly overexpress TTK, TBK1, Nek2, BUB1, and SGOI." (PMID 36494865, 2022). "We also analyzed a small cohort of primary breast tumor tissues for TTK and KLF5 expression." (PMID 30206215, 2018). "All the mitotic regulators above, including Nek2 and TTK, are also overexpressed in non-classified breast tumors." (PMID 36494865, 2022).
multiple myeloma (4 papers, 2014 to 2024). "In multiple myeloma, the TTK inhibitor OSU-13 can inhibit tumor growth in vitro and in vivo, improving patient prognosis." (PMID 38195567, 2024). "Our previous study demonstrated that as many as 5 of 17 genes found to be significantly up-regulated in ALDH1+ myeloma cells encode cell cycle-dependent protein kinases; specifically, CDC2, TTK, AURKA, AURKB and, of importance here, NEK2." (PMID 25230277, 2014).
pancreatic adenocarcinoma (4 papers, 2018 to 2024). "Increased levels of H3K18la in the promoter region in pancreatic adenocarcinoma (PDAC) promote the transcription of TTK protein kinase (TTK) and BUB1 mitotic checkpoint serine/threonine kinase B (BUB1B) to promote tumour progression." (PMID 39417674, 2024). "TTK is also over-expressed in pancreatic adenocarcinoma and plays a crucial role in maintaining the viability and proliferative potential of pancreatic adenocarcinoma cells." (PMID 29596435, 2018).
serous ovarian carcinoma (4 papers, 2021 to 2024). "The findings showed that high expression levels of BUB1B, BUB3, or TTK were associated with better survival rates in serous ovarian cancer patients treated with paclitaxel compared to patients with low expression levels." (PMID 38987356, 2024).
acute myeloid leukemia (3 papers, 2021 to 2023). Acute myeloid leukemia (AML) is a group of neoplasms arising from precursor cells committed to the myeloid cell-line differentiation. "This information can then be used to create context-specific network models in a way that does not depend on prior knowledge of KSRs or other information, and which can identify possible tumor vulnerabilities, for example, TTK in acute myeloid leukemia (AML)." (PMID 38164473, 2023).
anaplastic thyroid carcinoma (3 papers, 2011 to 2020). "In anaplastic thyroid cancer (ATC), E2F4 overexpression inhibits the transcription of the TTK in ATC cells." (PMID 33292231, 2020).
cervical carcinoma (3 papers, 2015 to 2021). A carcinoma arising from either the exocervical squamous epithelium or the endocervical glandular epithelium. "Upregulation of TTK has shown to be associated with malignant transformation of cervical cancer." (PMID 33829064, 2021). "TTK has been shown to be associated with metastasis via chromosomal instability, in a previous study, which aimed to identify genes associated with the progression and metastasis of advanced cervical cancer following radiotherapy." (PMID 25695263, 2015). "The candidate genes SPP1, FOXM1, LYN, COL6A3, CCL21, TTK and MELK at mRNA level, emerge as promising candidate markers for cervical cancer prognosis and also emerge as potential therapeutic drug targets." (PMID 33829064, 2021). "Specific inhibitors of TTK were screened using high throughput in vitro kinase assays, yielding AZ3146, MPI-0479605 and Mps1-IN-1 in inhibiting proliferation of cervical carcinoma cell Hela and colon carcinoma cell HCT-116, respectively." (PMID 26418879, 2015). "These previous findings and the results of the present analysis suggest that TTK, AURKA and BRCA2 may participate in the progression of cervical cancer." (PMID 25695263, 2015).
depression (3 papers, 2019 to 2024). "The major finding of our study is that TTK can alleviate the depressive symptoms induced by the astroglial degeneration model of depression in mice." (PMID 33628324, 2021). "Based on the findings, it appears that TTK may be a potent therapeutic agent for the treatment of depression based on its regulation of serotonin-mediated genes and peripheral serotonin level(s) in our in vitro and in vivo model." (PMID 30854015, 2019). "It is suggested that TTK may be one of the potential candidates for treating depression." (PMID 33628324, 2021). "Thus, TTK may exert beneficial effects on depression during pre- or/and postmenopausal periods via modulation of serotonin synthesis and metabolism." (PMID 30854015, 2019).
malignant mesothelioma (3 papers, 2019 to 2023). A malignant neoplasm of the pleura or peritoneum, arising from mesothelial cells. "CFI-402257, a selective orally bioavailable inhibitor of TTK, displays strong anti-tumor efficiency in combination with cisplatin/pemetrexed in malignant mesothelioma (MM)." (PMID 35850753, 2022). "In other cancer types, the overexpression of the Mps1-encoding TTK gene was correlated with poor patients’ outcome of HCC, malignant mesothelioma and so on." (PMID 30656409, 2019). "In addition, CFI-402257-mediated inhibition of TTK in malignant mesothelioma in vitro resulted in overturning the mitotic checkpoint, premature progression through mitosis, marked aneuploidy and mitotic catastrophe." (PMID 37770979, 2023). "Inhibition of TTK has emerged as a promising therapeutic strategy for the treatment of aneuploid tumors, with triple-negative breast cancer (TNBC) and malignant mesothelioma important focus of clinical development." (PMID 30656409, 2019).
oesophageal cancer (3 papers, 2021 to 2023). "TTK gene was overexpressed in the CSC-like cell populace remoted from human esophageal carcinoma phone strains as properly as in the human more than one myeloma stem cells sorted through aldehyde dehydrogenase 1 (ALDH1)." (PMID 36213825, 2022). "In advanced oesophageal cancer, IMP3 and other peptides (TTK, LY6K) have been used therapeutically as vaccines in phase II clinical trials." (PMID 37627115, 2023). "In oesophageal cancer, NY-ESO-1, MAGE-A, TTK and LAGE-1 are highly expressed and induce specific cytotoxic T lymphocytes (CTLs) to exert specific killing effects on tumour cells, and it was demonstrated by several clinical trials that immunotherapies are effective for oesophageal cancer." (PMID 34367148, 2021).
retinoblastoma (3 papers, 2021 to 2023). A malignant tumor that originates in the nuclear layer of the retina. "Bioinformatics analysis of multi-omics data also identified TTK, RRM2, and CDK1 as potential retinoblastoma molecular biomarkers." (PMID 38012786, 2023).
sarcoma (3 papers, 2017 to 2024). A usually aggressive malignant neoplasm of the soft tissue or bone. "We identified that inhibitors targeting the major mitotic kinases AURKA/B and TTK inhibited cell migration of diploid and tetraploid sarcoma cell subclones and invasion from diploid spheroids." (PMID 28035071, 2017). "We performed immunohistochemistry (IHC) on DDLS and WDLS to confirm protein expression of TTK, PBK and SPA17, as well as CTAs commonly expressed in sarcoma including NY-ESO-1 (included in Nanostring panel as CTAG1B), SSX2 and MAGE-A3, some of which that have been targeted by adoptive cell therapy." (PMID 38755218, 2024).
aneuploidy (2 papers, 2017 to 2022). Chromosomal disorder consisting of the presence a chromosomal abnormality in which there is an addition or loss of chromosomes within a set. "The overexpression of Nek2 and TTK also correlates with the higher aneuploidy indexes in NHB women." (PMID 36494865, 2022). "However, high levels of TTK correlate with chromosomal instability (CIN), which can lead to aneuploidy." (PMID 28415765, 2017).
endometrial endometrioid carcinoma (2 papers, 2022 to 2023). "Serous EC, a rare but more aggressive subtype of EC, had a much higher level of TTK expression than endometrial endometrioid carcinomas (EECs)." (PMID 36829176, 2023). "In another study, TTK was significantly up-regulated in an endometrial endometrioid carcinoma, with the knockdown of TTK inhibiting EC cell growth as well as inducing cell apoptosis in EC cell lines (AN3CA and HEC-1-B)." (PMID 36232772, 2022).
esophageal (2 papers, 2019 to 2022). "Several TAAs are highly expressed in EC, among which the most common TAAs have been confirmed in EC till date, including New York esophageal squamous cell carcinoma 1 (NY-ESO-1), TTK protein kinase (TTK), cancer-testis antigen 2 (CTAG2), and melanoma-associated antigen-A (MAGE-A)." (PMID 36119033, 2022).
gastric adenocarcinoma (2 papers, 2020 to 2025). "Also, the sensitivity and specificity of the expression changes of the AURKA, CEP55, DTL, and TTK genes for distinguishing colorectal and gastric adenocarcinoma from normal tissue were evaluated by ROC analysis." (PMID 40723362, 2025).
head and neck cancer (2 papers, 2024 to 2025). A primary or metastatic malignant neoplasm affecting the head and neck. "We used this database to assess the dependence of a large panel of head and neck cancer cell lines on the expression of PLK1, AURKA, TPR, NUF2, NDC80, and TTK." (PMID 39392349, 2024).
neuroblastoma (2 papers, 2022 to 2023). Neuroblastoma (NB) is the most common solid, extracranial childhood tumor. "Due to its essential role in chromosome alignment at the centromere during mitosis and its requirement for centrosome duplication, high TTK expression was observed in multiple cancer types, including neuroblastoma, where TTK was associated with poor overall survival." (PMID 37770979, 2023).
neutropenia (2 papers, 2022 to 2024). A decrease in the number of neutrophils found in the blood. "Specifically, it is tempting to postulate that BAL0891s unique profile could potentially alleviate the primary dose-limiting toxicity associated with PLK1-and TTK-specific inhibitors; namely hematologic toxicity (including neutropenia)." (PMID 39184047, 2024). "However, > 3 neutropenia was attributed to increases in TTK inhibitor." (PMID 36494865, 2022).
osteosarcoma (2 papers, 2022 to 2025). A usually aggressive malignant bone-forming mesenchymal neoplasm, predominantly affecting adolescents and young adults. "The treatment of HSP90 inhibitors also causes a reduction in tumor growth in mice carrying TTK-overexpressed osteosarcoma." (PMID 36077137, 2022). "The overexpression of TTK induces a rapid process of the cell cycle and significantly enhances osteosarcoma cell proliferation." (PMID 36077137, 2022). "A recent study has shown that HSP90 regulates threonine and tyrosine protein kinase (TTK) by directly interacting with TTK and preventing the proteasome degradation of TKK, resulting in the accumulation of TTK in osteosarcoma cells." (PMID 36077137, 2022). "The overexpressed kinases in osteosarcoma, liposarcoma, and leiomyosarcoma are mainly serine/threonine kinases (BUB1, CKD4, HUNK, LKKK1, NEK2, PBK, PLK1, and PLK4), whereas TTK has a dual role (Tyrosine and serine/threonine kinase) and only MELK presents tyrosine phosphorylation activity." (PMID 40723917, 2025).
acute lymphoblastic leukemia (1 paper, 2017). Leukemia with an acute onset, characterized by the presence of lymphoblasts in the bone marrow and the peripheral blood. "In contrast, treatment with TTK inhibitor did not reduce the viability of non-proliferating T cell acute lymphoblastic leukemia cells samples." (PMID 28415765, 2017). "To study the effect of TTK inhibition on non-dividing cells, that at the same time are relevant for cancer, we determined the effect of NTRC 0066-0 treatment on blood cell samples from ten different pediatric T-cell acute lymphoblastic leukemia (T-ALL) patients." (PMID 28415765, 2017).
aplastic anemia (1 paper, 2022). Anemia resulting from bone marrow failure (aplastic or hypoplastic bone marrow). "Abnormal gene expression exists in children with idiopathic severe aplastic anemia, and RRM2, TTK, and TYMS in children's MSCs are significantly down-regulated." (PMID 35082972, 2022).
atherosclerosis (1 paper, 2025). A disease characterized by the build-up of fatty material and calcium deposition in the arterial wall resulting in partial or complete occlusion of the arterial lumen. "To elucidate the mechanism underlying TTK upregulation in postinjury neointimal formation and atherosclerosis, we examined its regulation in VSMCs under pathological conditions." (PMID 39716891, 2025). "Parameters such as inflammatory cell infiltration and elastic fiber degradation should be assessed to provide a more comprehensive understanding of TTK's role in atherosclerosis." (PMID 39716891, 2025). "The involvement of the TTK/phosphorylated p120‐catenin (T310) pathway in vivo was examined in vascular injury and atherosclerosis models." (PMID 39716891, 2025). "This study selected CFI‐402257 to evaluate the therapeutic potential of TTK inhibitors in simultaneously preventing postinjury restenosis and treating atherosclerosis." (PMID 39716891, 2025). "The results of this study suggest that aberrant upregulation of TTK contributes to the phenotypic switching of VSMCs, leading to both postinjury neointima formation and atherosclerosis." (PMID 39716891, 2025). "The in vivo effects of TTK in promoting postinjury neointimal formation and atherosclerosis highlight its translational potential." (PMID 39716891, 2025). "Targeting TTK represents a promising approach to simultaneously prevent postinjury restenosis and treat atherosclerosis." (PMID 39716891, 2025). "Consistently, ChIP assays demonstrated increased interaction between IRF1 and the TTK promoter during postinjury neointimal formation and atherosclerosis." (PMID 39716891, 2025). "In conclusion, this study revealed that upregulated TTK promotes postinjury neointimal formation and atherosclerosis by facilitating VSMC phenotypic switching." (PMID 39716891, 2025). "Moreover, oral administration of a TTK inhibitor simultaneously exerted inhibitory effects on postinjury neointimal formation and atherosclerosis while preserving reendothelialization." (PMID 39716891, 2025). "First, while atherosclerosis development involves multiple processes, including phenotypic switching of VSMCs, inflammation, oxidative stress, and endothelial dysfunction, this study primarily focused on the role of TTK in VSMC phenotypic switching." (PMID 39716891, 2025). "Therefore, targeting TTK with specific inhibitors or alternative strategies presents a promising therapeutic approach to simultaneously prevent postinjury restenosis and manage atherosclerosis." (PMID 39716891, 2025). "Thus, targeting TTK using inhibitors or alternative strategies could be effective to simultaneously prevent postinjury restenosis and treat atherosclerosis." (PMID 39716891, 2025). "By re‐analyzing transcriptomic datasets from the Gene Expression Omnibus (GEO), this study identified TTK as a novel regulator of VSMC phenotypic switching in the contexts of postinjury neointimal formation and atherosclerosis." (PMID 39716891, 2025). "This study identifies TTK as a novel regulator of VSMC phenotypic switching, a critical process in the progression of postinjury neointimal formation and atherosclerosis." (PMID 39716891, 2025). "This study identifies TTK as a key inducer of vascular smooth muscle cell (VSMC) phenotypic switching in the context of postinjury neointimal formation and atherosclerosis." (PMID 39716891, 2025). "This study identifies TTK protein kinase (TTK) as a key regulator of vascular smooth muscle cell (VSMC) phenotypic switching in the context of postinjury neointimal formation and atherosclerosis." (PMID 39716891, 2025). "This study is the first to demonstrate the dual therapeutic potential of targeting TTK for treating atherosclerosis and preventing postinjury restenosis without adversely affecting endothelial repair." (PMID 39716891, 2025).
atherosclerosis (continued). "Negative correlations were observed between TTK mRNA levels and SMC contractile markers across two independent human datasets, further highlighting the role of TTK in promoting phenotypic switching during atherosclerosis progression." (PMID 39716891, 2025).
biliary tract cancer (1 paper, 2016). "TTK-567(SYRNEIAYL) epitope peptide was also used to elicit cytotoxic T lymphocytes to establish cancer vaccines in lung, esophageal and advanced biliary tract cancers." (PMID 27833085, 2016).
bladder tumor (1 paper, 2021). "TTK may also affect the bladder tumor microenvironment (TME) by affecting the number of immune cells." (PMID 34988018, 2021).